APOE (apolipoprotein E)
Diseases named in the same sentence as APOE in open-access papers (continued):
Sharing a sentence is not in itself a finding about the gene and the disease.
demyelination (6 papers, 2013 to 2023). "As a result, individuals with APOE may experience demyelination, cognitive loss, and increased death rates during a SARS-CoV-2 infection." (PMID 37508898, 2023). "To investigate the impact of apoE isoforms on microglial activation and function in response to neuronal injury, we utilized the toxin-induced demyelination model through CPZ treatment." (PMID 36419137, 2022). "APOE-/- mice showed impaired remyelination and increased phagocyte infiltration in a demyelination model." (PMID 36091018, 2022). "Taken together, in our study the behavioral and electrophysiological recovery in the LPC-induced demyelination model in mouse spinal cord provide another hint that apoE-mimetic COG112 does promote remyelination in the CNS." (PMID 25642353, 2013).
experimental autoimmune encephalomyelitis (6 papers, 2010 to 2021). An autoimmune demyelinating disease of the central nervous system that is produced experimentally in animals by the injection of homogenized brain or spinal cord in Freund's adjuvant. "APOE was associated with preventing disease progression in the experimental autoimmune encephalomyelitis (EAE) mouse model by regulating Th1 and Th17 responses." (PMID 34950038, 2021). "Consistently, apoE-knockout mice are more susceptible to and have greater disability in experimental autoimmune encephalomyelitis (EAE), a mouse model of MS." (PMID 25642353, 2013). "In this review, we summarized the current progress of the immunomodulatory functions of apoE, with special focus on the association of APOE ε allele with the clinical features of MS and of its animal model experimental autoimmune encephalomyelitis (EAE)." (PMID 20613949, 2010). "An apolipoprotein E (apoE)-mimetic peptide COG112 has previously demonstrated therapeutic efficacy on functional and histological recovery in a mouse experimental autoimmune encephalomyelitis (EAE) model of human MS." (PMID 25642353, 2013).
hematoma (6 papers, 2016 to 2025). A hematoma is a collection of blood from a vascular structure into an extravascular space. "The proposed mechanism may involve APOE ε2 predisposing to additional vessel rupture, leading to hematoma expansion and the formation of the island sign." (PMID 40051977, 2025). "Significantly more epidural hematomas on the acute CT were observed in the APOE-ε4(+) group." (PMID 35250800, 2022). "In addition to including the well-known lobar location of CAA-related ICH, these criteria included a subarachnoid space extension of ICH and finger-like projections with an irregular hematoma shape, as well as the presence of the apolipoprotein E (ApoE) ε4 genotype APOE-ε4." (PMID 33918041, 2021). "In conclusion we found that the small 5-amino acid base apoE-mimetic peptide CN-105 improved neurobehavioral outcomes, decreased edema, and increased neuronal survival over a 33-day testing period after preclinical ICH, but did not reduce hematoma volume or expansion." (PMID 27713572, 2016).
hyperlipemia (6 papers, 2013 to 2025). "We studied the effects of IMD on features of plaque vulnerability in hyperlipemia apolipoprotein E-deficient (ApoE−/−) mice." (PMID 33934111, 2021). "We first validated the establishment of hyperlipemia in ApoE−/− mice induced by a HFD." (PMID 40045452, 2025).
leukemia (6 papers, 2013 to 2025). A malignant (clonal) hematologic disorder, involving hematopoietic stem cells and characterized by the presence of primitive or atypical myeloid or lymphoid cells in the bone marrow and the blood. "Proteins Clus, Ceru, ApoE, ApoA4, ApoA1, Gels, S10A9, Ambp, Actb, Cata and Afam have an important role in leukaemia prognosis, mainly as distinctive signals for aggressive leukaemia cases." (PMID 25537633, 2015).
lung disease (6 papers, 2018 to 2025). "The predilection of APOE for pneumonia is consistent with past studies advocating that the role of APOE ɛ4 in lung disease may be linked to an increased risk of pulmonary complications." (PMID 36005151, 2022). "Therefore, additional studies will be required to assess whether the APOE ε4 allele is associated with modified pulmonary function in individuals with lung disease." (PMID 30412599, 2018). "Emerging evidence increasingly recognized that ApoE protein played a protective role in the development of lung diseases based on their ability to regulate inflammation and oxidative stress." (PMID 36425057, 2022). "In terms of pathogenesis, ApoE is protective against influenza A-driven lung disease, with mice lacking one or both ApoE alleles exhibiting more severe lung pathology and greatly reduced survival." (PMID 40439406, 2025). "In conclusion, we have identified that carriage of the APOE ε4 allele was associated with a decrease in the FEV1/FVC ratio as compared to carriers of the APOE ε3 allele among women without lung disease who participated in the LLFS." (PMID 30412599, 2018). "A limitation of this current study is that we were not able to assess if the APOE alleles modified pulmonary function in subjects with lung disease." (PMID 30412599, 2018). "The mechanisms by which the APOE ε4 allele might be associated with a relative reduction in airflow in women without lung disease are not known." (PMID 30412599, 2018). "The association between the APOE ε4 allele and a lower FEV1/FVC ratio persisted when the sub-group of LLFS women without lung disease was analyzed." (PMID 30412599, 2018). "Associations of the APOE ε2 and ε4 alleles with FEV1, FVC and FEV1/FVC in the sub-group of 3,832 genotyped LLFS participants without lung disease." (PMID 30412599, 2018).
mood disorder (6 papers, 2018 to 2025). A cognitive disorder a disturbance in which the person's mood is hypothesized to be the main underlying feature. "Given the potential implications of the APOE genotypes in brain disorders and their association with lipid levels, further investigation into the role of lipids and ApoE in mood disorders is warranted." (PMID 38673634, 2024). "Future investigations into the relationship between lipid metabolism, APOE, cognition and mood disorders are needed to shed light on the field." (PMID 38673634, 2024).
morbid obesity (6 papers, 2015 to 2025). An excess of body weight, normally defined as an individual with a body mass index greater than 35 or a body weight greater than one hundred percent of ideal body weight. "APOE polymorphism seems to have endocrine effects of clinical significance in subjects with morbid obesity." (PMID 35205269, 2022). "Nevertheless, the results indicate endocrine effects of clinical importance of APOE polymorphism in subjects with morbid obesity." (PMID 35205269, 2022). "This study explored associations between the APOE E alleles and comorbidity in subjects with morbid obesity." (PMID 32646381, 2020). "The paramount aim of this study was to explore associations between the APOE E alleles and psychosomatic disorders and inflammatory markers in subjects with morbid obesity." (PMID 32646381, 2020). "Despite these major advances in the understanding of the role of APOE in morbid obesity, the precise mechanisms underlying its opposing site-specific effects, including the effector molecules mediating the cross-talk between brain APOE and WAT mitochondrial metabolic activity, remain unclear." (PMID 29770778, 2017). "The findings indicate APOE-mediated effects on body weight and metabolic functions in subjects with morbid obesity." (PMID 35205269, 2022). "The study aimed primarily at exploring the prevalence of APOE E4 in subjects with morbid obesity and the effect of E4 on conservative and surgically induced weight reduction." (PMID 32646381, 2020). "ApoE knockout (ApoE−/−) mice provided a high fat western diet develop morbid obesity and have evidence of chronic inflammation." (PMID 25852821, 2015). "Additionally, recent studies have shown a link between ApoE and morbid obesity in experimental animals." (PMID 34796296, 2021). "Here, we provide a critical review of the latest facts on the role of APOE in morbid obesity." (PMID 29770778, 2017). "Recent studies in mice strongly suggest a link between apolipoprotein E (APOE) and morbid obesity." (PMID 41354325, 2025). "Contrasting this outdated view, the current data show that increasing hepatically expressed APOE may exert a significant beneficial effect against WAT expansion and morbid obesity development." (PMID 29770778, 2017).
parasitemia (6 papers, 2013 to 2024). "After 6 weeks of infection, apoE KO mice exhibited reduced footpad swelling and parasitemia similar to C57BL/6 controls, confirming that both strains are resistant to infection with L. major." (PMID 23710353, 2013). "The non-symptomatic ApoE−/− mice developed hyperparasitemia; the level of parasitemia in the P. berghei ANKA-infected WT mice only reached 15–20%, but the ApoE−/− mice that did not develop ECM had a parasitemia as high as 70–80%." (PMID 27647324, 2016).
peripheral arterial disease (6 papers, 2016 to 2023). A disorder of the arteries supplying the upper and lower extremity and the visceral organs. "It is well accepted that genetic factors are associated with peripheral artery disease, and APOE polymorphism plays a role in this issue, partially in relation to lipid levels." (PMID 37629219, 2023). "The apolipoprotein E (ApoE) gene polymorphism has been found to influence plasma lipid concentration, and its correlation with peripheral arterial disease (PAD) has been investigated." (PMID 32211081, 2020). "The aim of the study is to investigate the relationship between APOE genotypes and peripheral revascularization in a cohort of patients affected by advanced peripheral arterial disease (PAD) at a prolonged follow-up." (PMID 37629219, 2023).
renal dysfunction (6 papers, 2009 to 2025). "The dyslipidemic profile is similar to that of type III dyslipoproteinemia with Apolipoprotein E values that are often high; proteinuria and renal dysfunction are present." (PMID 20062740, 2009). "Finally, potential modifiers such as renal dysfunction or APOE ε4 dosage effects were not addressed—factors known to influence plasma tau levels." (PMID 40589622, 2025).
acute myeloid leukemia (5 papers, 2016 to 2024). Acute myeloid leukemia (AML) is a group of neoplasms arising from precursor cells committed to the myeloid cell-line differentiation. "ApoE has been identified as an extracellular binding protein of leukocyte immunoglobulin-like receptor B4 (LILRB4), and disruption of the LILRB4/apoE interaction blocks the development of acute myeloid leukemia." (PMID 37310025, 2023). "In more recent findings, LILRB4 was shown to bind CD166 (activated leukocyte adhesion molecule, ALCAM) and serum apolipoprotein E (APOE), which mediate tumor cell growth and acute myeloid leukemia, respectively." (PMID 38397424, 2024). "Our previous study reported that apoE activated LILRB4 signaling to mediate immune escape and extramedullary infiltration of acute myeloid leukemia (AML) by cell–cell independent manner." (PMID 38951916, 2024). "Additionally, we discovered that the apoE-mimetic peptide OP449 (formerly COG449, Oncotide Inc) inhibits SET, resulting in restoration of PP2A tumor suppressor activity in chronic myelogenous leukemia (CML) and acute myelogenous leukemia (AML)." (PMID 27705940, 2016).
allergic disease (5 papers, 2021 to 2024). An immune response that occurs following re-exposure to an innocuous antigen, and that requires the presence of existing antibodies against that antigen. "Furthermore, APOE has been associated with the phenotype of maternal diabetes, a condition that correlates with a higher risk of allergic disease in offspring." (PMID 38773393, 2024). "Previous reports implicated a number of proteins, including apolipoprotein E, cytoplasmic phospholipase A2, prostaglandin and calpain with anti-PrP antibody-mediated ‘apoptosis’, however, these proteins are also known to play an important role in allergy." (PMID 34394070, 2021). "For instance, levels of APOE in the bronchoalveolar fluid derived from patients with hypersensitivity pneumonitis were shown to be significantly high and APOE was suggested to play an important role in this allergic disease." (PMID 34394070, 2021). "According to the ceRNA hypothesis, literature review revealed that miR-142–5p is significantly expressed in the aortic plaques of AS patients and ApoE−/− mice, as well as in the skin of subjects with allergic reactions." (PMID 39072329, 2024). "Moreover, impaired delayed type hypersensitivity responses were observed in APOE-null mice, demonstrating the important role of APOE in regulating allergy." (PMID 34394070, 2021). "In early childhood, allergies, reduced growth rate, short stature, and abnormal fat metabolism [high FFA and high apolipoprotein E (ApoE)] gradually appear." (PMID 35140738, 2021).
argyrophilic grain disease (5 papers, 2017 to 2022). A tauopathy characterized pathologically by the presence of silver stain positive lesions called argyrophilic grains, oligodendrocytic coiled bodies, and neuronal tau-positive pretangles. "Supporting this, APOE*ε2 has been associated with increased risks of PSP and argyrophilic grain disease (AGD) in humans." (PMID 33148290, 2020). "Fifth, we examined APOE effects on a variety of FTLD related pathologies including FTLD-tau 3R Pick’s, 4R PSP, CBD, and argyrophilic grain disease, and FTLD-TDP-43." (PMID 32948752, 2020). "Rather, we sought to understand the impact of APOE genotype on amyloid plaques and NFTs, other protein aggregation abnormalities involved in FTLD and related tauopathies (TDP-43, Pick’s, PSP, CBD, argyrophilic grain disease), and alpha-synuclein Lewy bodies." (PMID 32948752, 2020).
behavioral disorders (5 papers, 2016 to 2024). "In this study, we have investigated some of the demographic factors most relevant to the cognitive traits, such as age at disease onset, disease duration, and education; clinical features as motor signs and behavioral disorders; APOE genotype and vascular diseases and medical histories." (PMID 36389060, 2022).
diabetic cardiomyopathy (5 papers, 2018 to 2024). Diabetic cardiomyopathy is a disorder of the heart muscle in people with diabetes. "In conclusion, our study provides compelling evidence that diabetic ApoE−/− mice exhibit hallmark features of diabetic cardiomyopathy (such as adverse remodeling and diastolic dysfunction)." (PMID 39563316, 2024). "This provides strong evidence for the therapeutic efficacy of MSC-Exos in mitigating pathology associated with diabetic cardiomyopathy in ApoE KO mice." (PMID 38390337, 2024). "Given that chronic low-grade inflammation plays an important role in the development of diabetic cardiomyopathy, we utilized ApoE−/− mice on a C57BL/6 background in this study." (PMID 39563316, 2024). "In vivo, RAGE ligands were significantly upregulated in a diabetic cardiomyopathy apoE−/− mouse model in comparison with controls (nondiabetic apoE−/−)." (PMID 35251212, 2022).
Encephalopathy (5 papers, 2015 to 2026). Encephalopathy is a term that means brain disease, damage, or malfunction. "First, a multicentre large CSF proteomic study would be required to confirm the co-upregulation of APOE and APP in CM patients relative to age-matched patients with non-plasmodial encephalopathies and healthy community controls." (PMID 39023792, 2025).
esophageal squamous cell carcinoma (5 papers, 2023 to 2025). Esophageal squamous cell carcinoma (ESCC) is a type of esophageal carcinoma (EC) that can affect any part of the esophagus, but is usually located in the upper or middle third. "Finally, high numbers of MΦ co-expressing APOC1 and APOE were found in metastatic lymph nodes of esophageal squamous cell carcinoma, a cancer with a metastatic pattern similar to OSCC." (PMID 40432828, 2025). "Furthermore, we compared the highly expressed genes of APOC1+ APOE+ macrophages enriched in esophageal squamous cell carcinoma (ESCC) lymph nodes, which exhibit a similar tendency to lymph node metastasis as OSCC." (PMID 39236316, 2024). "We analyzed two single-cell RNA sequencing (scRNA-seq) datasets (GSE145370 and GSE160269) of esophageal squamous cell carcinoma to identify a novel TREM2-positive TAM subpopulation characterized by upregulation of TREM2, C1QC, C1QB, C1QA, SPP1, and APOE." (PMID 37187751, 2023). "Global single-cell transcriptome analysis using data from clinical trials demonstrated that TAMs highly expressed APOE, APOC1, and SPP1 genes in patients with esophageal squamous cell carcinoma (ESCC) post-neoadjuvant chemotherapy, and this leads to an increase in M2-like macrophages." (PMID 38787372, 2024).
Hallucinations (5 papers, 2012 to 2025). Perceptions in a conscious and awake state that, in the absence of external stimuli, have qualities of real perception. "Each additional copy of the APOE E4 allele conferred a 22% increase in the odds of reporting hallucinations." (PMID 40926580, 2025). "While some APOE SNPs had nominally significant association with hallucinations, they did not survive Bonferroni correction." (PMID 39974048, 2025).
hepatitis B virus infection (5 papers, 2017 to 2026). A viral infection caused by the hepatitis B virus. "Thus, the C1q-ApoE complex is a new pathological hallmark of viral hepatitis B and C and NAFLD." (PMID 36304458, 2022). "Further, four of the most significantly enriched KEGG immune pathways in the CSF and plasma were also identified in APOE ε4 carriers in a disease-independent manner, including EBV, hepatitis B, viral carcinogenesis and pathogenic Escherichia coli infection." (PMID 40665049, 2025). "It will be interesting to determine whether the levels of apoE and/or apoE-containing lipoproteins in the plasma of hepatitis B patients correlate with the viral load and/or the outcomes of HBV infection." (PMID 31393946, 2019).
HIV dementia (5 papers, 2006 to 2020). "Further, studies of Alzheimer and HIV dementia brains and aortic tissue levels of APOE knockout mice have found APOE genotype alters ceramide levels in these compartments." (PMID 26193443, 2015).
inflammatory bowel disease (5 papers, 2005 to 2025). A spectrum of small and large bowel inflammatory diseases of unknown etiology. "A similar decrease in expression of anti-oxidant enzymes was observed in ApoE-deficient mice in response to chronic inflammation, and inflammatory bowel disease (IBD)." (PMID 15790412, 2005). "While these CP-related findings differ from intestinal CD, we could detect a higher abundance of predictive protein markers for anti-TNF-α therapy in CD esophagitis as described in serum of inflammatory bowel disease (IBD) patients such as CRP, ITGAV, APOE, and CLU (Fig. EV4C)." (PMID 39901020, 2025).
leukocytosis (5 papers, 2012 to 2024). "Studies have shown that ApoE-/- mice can develop severe leukocytosis and lack a cholesterol efflux mechanism, and their accumulated cholesterol can lead to an inflammatory response." (PMID 38491412, 2024).